METTL9 (methyltransferase 9, His-X-His N1(pi)-histidine)
Diseases named in the same sentence as METTL9 in open-access papers:
METTL9 is named in the same sentence as 19 diseases in open-access papers, as found by Europe PMC text mining. Sharing a sentence is not in itself a finding about the gene and the disease. The quoted sentences say what the papers report.
hepatocellular carcinoma (5 papers, 2023 to 2025). A malignant tumor that arises from hepatocytes. "METTL9 has been associated with several diseases, such as hepatocellular carcinoma, scirrhous gastric cancer, HIV, and bacterial infection." (PMID 40451431, 2025). "Targeting METTL9 significantly inhibits the growth of hepatocellular carcinoma patient-derived xenografts and correlates with increased metastatic activity in human gastric cancer." (PMID 38831425, 2024). "METTL9 knockdown reduces the expression levels of SLC7A11, a key inhibitor of ferroptosis, thereby indirectly inducing ferroptosis in hepatocellular carcinoma (HCC)." (PMID 41194259, 2025). "Methytransferase-like proteins 9 (METTL9) has been characterized as an oncogene in several cancers, however, its role in hepatocellular carcinoma (HCC) remains unknown." (PMID 38017014, 2023). "METTL9 promotes hepatocellular carcinoma progression by inhibiting ferroptosis through upregulation of SLC7A11, with its knockdown significantly reducing tumor viability, migration, and invasion, suggesting METTL9 as a potential therapeutic target for HCC." (PMID 39315094, 2024).
gastric cancer (3 papers, 2022 to 2024). A primary or metastatic malignant neoplasm involving the stomach. "We found that elevated methyltransferase-like 9 (METTL9) is closely associated with the acquisition of metastatic activity in human scirrhous gastric cancers." (PMID 35402738, 2022). "First, the present findings indicate that elevated METTL9 expression is closely associated with peritoneal dissemination in human scirrhous gastric cancers, as was clear by the evidence obtained from our metastatic cell experiments." (PMID 35402738, 2022). "The rise of METTL9 is associated with peritoneal metastasis of gastric cancer." (PMID 38130905, 2023). "As a result, we discovered that elevated METTL9 expression can function to positively promote peritoneal dissemination in scirrhous gastric cancers." (PMID 35402738, 2022). "The stable knockdown of METTL9 via an shRNA vector technique in our original metastatic cells from scirrhous gastric cancer patients significantly inhibited migration and invasion." (PMID 35402738, 2022). "Here we aim to investigate the functions of METTL9 genes in the peritoneal dissemination of human scirrhous gastric cancer using our metastatic cell model and clinical samples (gastric cancer tissues) from patients." (PMID 35402738, 2022). "METTL9 expression was significantly elevated in cancer tissues from patients with scirrhous gastric cancers." (PMID 35402738, 2022). "Further, using clinical tissue specimens of gastric cancers, we showed that METTL9 elevation is characteristic in patients with peritoneal dissemination, indicating that METTL9 can be a candidate of molecular targets for inhibiting peritoneal dissemination." (PMID 35402738, 2022). "Our findings demonstrated that METTL9 is a suitable molecular target candidate for the strategy of inhibiting peritoneal dissemination of scirrhous gastric cancer." (PMID 35402738, 2022). "METTL9 can be a candidate of molecular targets to inhibit peritoneal dissemination of scirrhous gastric cancers." (PMID 35402738, 2022). "•METTL9 knockdown reduces mitochondrial Complex I activity to decrease cell migration and invasion in metastatic scirrhous gastric cancer." (PMID 35402738, 2022). "Second, we found that METTL9 protein is predominantly localized in mitochondria in our metastatic scirrhous gastric cancer cells." (PMID 35402738, 2022). "This study showed for the first time that METTL9 plays a significant role in peritoneal dissemination of human scirrhous gastric cancer." (PMID 35402738, 2022). "Because elevated METTL9 is observed in both primary cancer tissues and disseminated tissues, we are now vigorously examining METTL9 expression in circulating tumor cells in the bloodstream in gastric cancer patients with peritoneal dissemination." (PMID 35402738, 2022). "Finally, using a public database, we analyzed the prognostic relevance of METTL9 gene expression in patients with poorly differentiated gastric cancers." (PMID 35402738, 2022). "Thus, METTL9 is a specific marker protein that arrests MICs in the bloodstream in gastric cancer patients." (PMID 35402738, 2022). "•Elevated METTL9 correlates with metastasis in human scirrhous gastric cancer." (PMID 35402738, 2022). "•METTL9 protein localizes mainly in mitochondria in metastatic scirrhous gastric cancer." (PMID 35402738, 2022). "In particular, in primary gastric cancer tissues from patients with peritoneal dissemination (third black bar) METTL9 expression was significantly higher than that in primary gastric cancer tissues from patients without peritoneal dissemination (second white bar)." (PMID 35402738, 2022).
liver cancer (3 papers, 2022 to 2023). An epithelial or non-epithelial malignant neoplasm that arises from the liver. "To further validate the results of TCGA data, we performed immunohistochemistry (IHC) staining on liver cancer tissue microarray at Sun Yat-Sen University Cancer Center (SYSUCC) and assessed the relationship between METTL9 expression level and patient survival prognosis." (PMID 38017014, 2023). "Our data revealed significant upregulation of METTL9 expression in liver cancer tissues compared to non-cancerous tissues, Additionally, patients with high METTL9 expression showed a significantly shorter overall survival." (PMID 38017014, 2023).
colorectal cancer (2 papers, 2024). A primary or metastatic malignant neoplasm that affects the colon or rectum. "The expression of circ-METTL9 was significantly up-regulated in colorectal cancer tissues and significantly elevated in patients with advanced colorectal cancer tumors." (PMID 39289775, 2024). "Overexpression of circ-METTL9 promotes colorectal cancer cell proliferation and migration in vitro, as well as colorectal cancer tumor growth and metastasis in vivo." (PMID 39289775, 2024). "RNA immunoprecipitation experiments on colorectal cancer have suggested that circ-METTL9, containing multiple exons, may serve as a miRNA sponge, interacting with miR-551b-5p." (PMID 39155349, 2024).
osteoporosis (2 papers, 2024 to 2025). A condition of reduced bone mass, with decreased cortical thickness and a decrease in the number and size of the trabeculae of cancellous bone (but normal chemical composition), resulting in increased fracture incidence. "The results showed that METTL9 overexpression effectively inhibited adipose tissue growth and reduced bone loss in the mouse osteoporosis model." (PMID 40414869, 2025). "Thus, we hypothesize that the progression of osteoporosis is closely associated with the downregulation of METTL9 expression." (PMID 40414869, 2025). "Our study systematically identified seven candidate hub genes (PDP1, ALS2CL, VLDLR, PLEKHA6, PPP1CB, MOSPD2, and METTL9) through a combination of various bioinformatics analyses and machine learning algorithms, and provided a nomogram for diagnosing sarcopenia associated with osteoporosis." (PMID 38831425, 2024). "In conclusion, METTL9 plays a crucial role in regulating the balance between the adipogenic and osteogenic differentiation of MSCs in osteoporosis, and thus, it is a potential target for the diagnosis and treatment of osteoporosis." (PMID 40414869, 2025). "In summary, we confirmed that METTL9 expression was significantly downregulated in the osteoporosis group at the bioinformatics, tissue, and cellular levels." (PMID 40414869, 2025). "In conclusion, these results suggest that increasing METTL9 levels in osteoporotic mice can effectively mitigate osteoporosis progression, making METTL9 a potential target for the diagnosis and treatment of osteoporosis." (PMID 40414869, 2025). "In this study, we found that METTL9 expression was downregulated in osteoporosis, and further adipogenic functional experiments revealed that METTL9 negatively regulated the adipogenic differentiation of MSCs both in vitro and in vivo." (PMID 40414869, 2025). "Our findings indicate that METTL9 expression is downregulated in osteoporosis, and we further demonstrated that METTL9 negatively regulates MSC adipogenic differentiation both in vitro and in vivo." (PMID 40414869, 2025). "We identified 7 candidate hub genes (PDP1, ALS2CL, VLDLR, PLEKHA6, PPP1CB, MOSPD2, METTL9) and constructed column line plots for osteoporosis combined with sarcopenia." (PMID 38831425, 2024). "A notable finding is the identification of 7 key candidate genes (PDP1, ALS2CL, VLDLR, PLEKHA6, PPP1CB, MOSPD2, and METTL9), and the development of a nomogram for diagnosing osteoporosis in sarcopenia patients." (PMID 38831425, 2024). "In this study, we aimed to reveal the biological role of METTL9 in the progression of osteoporosis." (PMID 40414869, 2025). "however, the role of METTL9 in the imbalance of MSC differentiation in osteoporosis remains unclear." (PMID 40414869, 2025). "In summary, our results suggest that the METTL9/SLC39A7 axis may be a promising diagnostic and therapeutic target for osteoporosis." (PMID 40414869, 2025). "To investigate whether METTL9 could be used as a therapeutic target for osteoporosis, we injected an adenovirus overexpressing METTL9 into a mouse model of osteoporosis." (PMID 40414869, 2025). "Additionally, the upstream regulatory mechanisms that lead to reduced METTL9 expression in individuals with osteoporosis remain unclear." (PMID 40414869, 2025). "To further explore the mechanism by which METTL9 participates in MSC adipogenic differentiation, we compared the potential substrates of METTL9 with the DEGs from the GSE35958 (osteoporosis) dataset." (PMID 40414869, 2025). "To further verify whether METTL9 could be used as a therapeutic target for osteoporosis in vivo, we established an OVX-induced model of osteoporosis in mice and injected rAAV9-METTL9 into the mice via the tail vein 1 week later." (PMID 40414869, 2025).
abscesses (1 paper, 2024). "Compared to WT control mice, Mettl9−/− mice exhibited a significantly decreased lesion area and S. aureus burden in the abscess tissue." (PMID 37522633, 2024). "Similarly, Mettl9−/− mice exhibited a significantly decreased lesion area and S. aureus burden in the abscess tissue compared to WT controls." (PMID 37522633, 2024).
fungal infection (1 paper, 2021). "Given that S100A9 exerts an antimicrobial activity, probably by chelation of zinc essential for the growth of bacteria and fungi, METTL9-mediated S100A9 methylation might be involved in the innate immune response to bacterial and fungal infection." (PMID 34562450, 2021).
Neurodevelopmental delay (1 paper, 2025). "Given its high expression in vertebrate nervous system and its potential association with neurodevelopmental delay, we dissected Mettl9 role during neural development." (PMID 40745158, 2025).
prostate carcinoma (1 paper, 2022). A carcinoma that arises from epithelial cells of the prostate gland. "A recent report showed that METTL9-mediated methylhistidine modification on zinc transporter SLC39A7 regulates the growth of prostate cancers both in vitro and in vivo." (PMID 35402738, 2022).
tumor (5 papers, 2022 to 2025). "Moreover, METTL9-dependent methylation of certain zinc transporters is associated with tumour growth." (PMID 40745158, 2025). "In this model, we used a specific siRNA sequence to target and silence METTL9 expression to observe its effect on tumor growth." (PMID 38017014, 2023). "Compared to the control group, the tumor weights were significantly lighter in the METTL9 knockdown group." (PMID 38017014, 2023). "It was found that METTL9 overexpression led to greater proliferation capacity, larger tumor size, and heavier tumor weights compared to the vector group." (PMID 38017014, 2023). "Our experiments verified that METTL9 knockdown significantly impedes tumor growth in PDX model, highlighting its potential utility as a therapeutic target for HCC." (PMID 38017014, 2023). "GEO datasets (GSE36376 and GSE76427) also demonstrated significantly higher METTL9 expression in tumor tissues compared to non-tumor tissues." (PMID 38017014, 2023). "Mechanistically, we found that METTL9 promoted tumor progression by upregulating the expression of SLC7A11, which subsequently decreases lipid oxidative damage and enhances antioxidant capacity, thereby inhibiting tumor-cell ferroptosis." (PMID 38017014, 2023). "It is upregulated in many tumours (where its expression level correlates with poor prognosis) and decreasing METTL9 expression in hepatocellular carcinoma cells slows down their proliferation and ability to generate tumours in vivo as well as their invasiveness." (PMID 40745158, 2025). "Moreover, METTL9 was essential for tumor growth by regulating zine transport proteins inducing ER stress in prostate cancer." (PMID 38017014, 2023). "METTL9 expression levels were generally upregulated in tumor tissues, including HCC." (PMID 38017014, 2023). "The results showed that Lip-1 partially restored tumor size and weight of METTL9 knockdown group." (PMID 38017014, 2023). "Knockdown of METTL9 could obviously decelerate HCC tumor growth." (PMID 38017014, 2023). "To assess whether METTL9 could be a potential therapeutic target for HCC, we utilized a patient-derived xenograft (PDX) tumor model in NSG mice." (PMID 38017014, 2023).
cancer (4 papers, 2022 to 2025). A tumor composed of atypical neoplastic, often pleomorphic cells that invade other tissues. "METTL9, a methyltransferase, plays a crucial role in histone methylation and is implicated as an oncogene in various cancers." (PMID 38831425, 2024). "Similarly to other METTL proteins, METTL9 has also been linked to cancer biology." (PMID 40745158, 2025). "To elucidate the potential role of METTL9 in cancers, we initially investigated the expression levels of METTL9 in tumors using The Cancer Genome Atlas (TCGA) dataset." (PMID 38017014, 2023). "Our study provided the first evidence that METTL9 was a new ferroptosis regulator and had the property of inhibiting ferroptosis in malignant tumors." (PMID 38017014, 2023). "Although METTL9 has been characterized as an oncogene in several cancers, its biological function in HCC is poorly understood and the knowledge of underlying molecular mechanism is limited, and remains to be elucidated." (PMID 38017014, 2023). "In other words, inhibition of METTL9 activity can provide an effective therapeutic strategy against cancer metastasis." (PMID 35402738, 2022). "They must have characteristics that are advantageous for cancer metastasis, and elevated METTL9 is one characteristic of MICs." (PMID 35402738, 2022). "The findings that METTL9 facilitates evasion of ferroptosis provide a proof-of-principle, and its potential oncogenic function highlights its significance as a therapeutic target for cancer treatment." (PMID 38017014, 2023). "Therefore, elevated METTL9 logically contributes to cancer cells’ acquisition of metastatic activity." (PMID 35402738, 2022). "The present study is the first to connect elevated METTL9 with cancer metastasis." (PMID 35402738, 2022). "However, besides its role in cancer and in immune response, the biological function of METTL9 in physiological and developmental processes has remained unknown." (PMID 40745158, 2025). "We were also motivated because the functions of METTL9 in cancer development and progression had not been elucidated yet." (PMID 35402738, 2022). "We suspect that this might have been overlooked by other works because of a lack of good anti-METTL9 antibodies, as well as the exclusive use of METTL9 over-expression systems in cancer cell lines." (PMID 40745158, 2025).
bacterial infection (1 paper, 2021). "The biological function of METTL9 has yet to be revealed; however, our data point out a possible link between METTL9 activity and innate immune response to bacterial infection through histidine methylation of S100A9." (PMID 34562450, 2021). "Thus, METTL9-mediated S100A9 methylation appears to be involved in the innate immune response to bacterial infection." (PMID 34562450, 2021). "Thus, understanding the contribution of METTL9-mediated histidine methylation of S100A9 in particular to immune response holds the potential of identifying new therapeutic targets and developing alternative treatment strategies for bacterial infections." (PMID 34562450, 2021).
infection (1 paper, 2023). The state of being infected such as from the introduction of a foreign agent such as serum, vaccine, antigenic substance or organism. "Given that S100A9 might play an antibacterial role by chelating the zinc necessary for growth of pathogenic bacteria, METTL9 mediated S100A9 methylation may participate in the innate immune response to infection." (PMID 37671148, 2023).
neurodegenerative disease (1 paper, 2025). A disorder of the central nervous system characterized by gradual and progressive loss of neural tissue and neurologic function. "Interestingly, METTL9 expression in the adult brain peaks in the striatum, which is responsible for some of the cognitive and behavioural functions impaired in neurodegenerative diseases." (PMID 40745158, 2025).
neurodevelopmental disorder (1 paper, 2025). A behavioral and cognitive disorder with onset during the developmental period that involves impaired or aberrant development of intellectual, motor, or social functions. "Since the phenotypes associated with these METTL9-containing deletions suggested a putative role for METTL9 in neurodevelopmental disorders, we assessed METTL9 expression in the developing brain during prenatal life." (PMID 40745158, 2025).
METTL9 also shares sentences with these, for which no sentence is quoted: Hypertension (1 paper); Intellectual disability (1); sarcopenia (1); Sepsis (1).